CRP (C-reactive protein)
Diseases named in the same sentence as CRP in open-access papers (continued):
Sharing a sentence is not in itself a finding about the gene and the disease.
COVID-19 (continued). "Laboratorial parameters from blood samples have been shown in COVID-19 patients, such as D-dimer, ferritin and C-reactive protein." (PMID 33270751, 2020). "The top five parameters that influenced the severity of COVID-19 were CRP, ALB, age ≥60 years, comorbidity, and LDH." (PMID 33330318, 2020). "ADL impairment, fever, and initial CRP were poor prognostic factors in elderly patients with COVID-19." (PMID 33291617, 2020). "Recent research showed that the serum CRP levels can be used to effectively assess disease severity in COVID-19 patients." (PMID 33031060, 2020). "The results of the current meta-analysis indicated that the CRP level is positively correlated with the severity of COVID-19." (PMID 33244370, 2020). "Herein, rationale is given for interpretation of CRP blood levels as a simple, rapid, and cost-effective way to assess disease severity and help guide therapeutic options in COVID-19 patients." (PMID 32588812, 2020). "Patient-level data shows a notable OR of 3.4 with 95% CI (2.15 to 5.4) for high CRP in severe COVID-19 patients." (PMID 32876941, 2020). "This idea is further supported by the increased level of lactate dehydrogenase (LDH) and C-reactive protein (CRP) in the blood of COVID-19 patients." (PMID 32883951, 2020). "Recent reports suggest that CoViD-19 disease is characterized by an exaggerated release of acute phase reactants that includes C-reactive protein (CRP), serum amyloid A, and ferritin, suggesting a rapid activation of the innate immune response." (PMID 32574269, 2020). "OPLS-DA identified that the top five influencing parameters for COVID-19 severity were CRP, ALB, age ≥60 years, comorbidity, and lactate dehydrogenase (LDH) level." (PMID 33330318, 2020). "COVID-19 patients with DM showed as older ages, higher levels of C-reactive protein (CRP), myoglobin, alanine transaminase (ALT), and aspartate transaminase (AST)." (PMID 33381599, 2020). "Age, high-sensitivity C-reactive protein level, lymphocyte count, and d-dimer level of COVID-19 patients at admission are the factors concluded to be associated with increased mortality risk in the study." (PMID 33102426, 2020). "A report showed that COVID-19 patients had an increase in neutrophils, interleukin (IL-6), and C-reactive protein (CRP) and a decrease in lymphocytes." (PMID 33101440, 2020). "Patients with a severe course of COVID-19 had significantly increased interleukin (IL)-6, C-reactive protein (CRP), and leukocyte counts and significantly decreased lymphocyte counts." (PMID 32443442, 2020). "CRP is a widely available inflammatory marker which has been independently observed as a biomarker of COVID-19 severity." (PMID 33296405, 2020). "This idea is supported by the observed elevation in D-dimers, C-reactive protein (CRP), ferritin, and procalcitonin in severe COVID-19 patients." (PMID 32922406, 2020). "Dalje, CRP je nezavisno povezan sa težinom bolesti COVID-19 (OR = 1,11, 95% IC i or = 1,13, 95% IC)." (PMID 33312067, 2020). "A study conducted in China among COVID-19 patients presented at fever clinic, suggested the use of eosinophilia and CRP, which showed relatively high sensitivity and specificity for detection and isolation." (PMID 33456651, 2020). "COVID-19 is often characterized by elevated inflammatory response manifested by C-reactive protein (CRP) overexpression, pro-inflammatory cytokines production (Il-6, IL-10, IL-1), higher TNF-α, neutrophil count, D-dimer, and blood urea." (PMID 33383838, 2020). "Across the 23 evaluated observational studies, the association between the levels of inflammatory markers and the severity of COVID-19 and the levels of CRP, TNF-, and IL-6 was significantly high in the group with severe COVID-19 compared to the mild group." (PMID 33244370, 2020). "An excessive increase of C-reactive protein (CRP), IL-6, and ferritin observed in COVID-19 cases was termed CRS in analogy to similar findings in hemophagocytic lymphohistiocytosis and CAR-T cell therapy." (PMID 33154972, 2020).
COVID-19 (continued). "This is the first study on the prognostic power of CRP for moderate-severe CT grading and inpatient duration in COVID-19 infected patients." (PMID 32414383, 2020). "Further, increased CRP and progressive decrease in the absolute lymphocyte count have also been observed in severe COVID-19 patients." (PMID 32766268, 2020). "More than half of patients had COVID-19 related inflammation indicated by elevated C-reactive protein (277 of 430 [64.4%]) and procalcitonin (164 of 398 [41.2%])." (PMID 33051404, 2020). "The patient had mild type COVID-19, with normal results for routine blood parameters and inflammation markers (C-reactive protein and procalcitonin)." (PMID 32543348, 2020). "This study found that the CRP level at admission represent a simple and independent factor that can be useful for early detection of severity during COVID-19 and the easy guidance of primary care." (PMID 33312067, 2020). "Cox regression analysis indicated that older age and higher serum levels of interleukin-6, C-reactive protein, procalcitonin, and lactate at admission significantly predicted the progression of COVID-19." (PMID 33239109, 2020). "Measurement of ferritin and C-reactive protein, as well as quantification of interleukin-6 on indication, should be performed in patients with severe COVID-19." (PMID 33054818, 2020). "Titres of antibodies are higher in elderly COVID-19 patients, and this is positively correlated to plasma CRP levels but negatively correlated to lymphocyte counts and suggests a possible link between humoural and cellular immunity." (PMID 32922406, 2020). "The comparison of the data among the three groups showed a positive association between creatine kinase-MB, lactic dehydrogenase, D-dimer, fibrinogen, procalcitonin (PCT), hs-CRP and COVID-19 severity." (PMID 32727465, 2020). "The chest CT scan results of COVID-19 patients are characteristic, being correlated with CRP and D-dimer levels." (PMID 32968416, 2020). "COVID-19 patients also have significantly raised C-reactive protein (CRP) and serum ferritin levels." (PMID 33153161, 2020). "In our study, this nomogram based on three variables, CRP, PaO2/FiO2, and cTnI, can provide a more accurate assessment and prediction of mortality at admission for COVID-19 patients." (PMID 32850612, 2020). "Regarding the biochemistry data, the COVID-19 patients had a rise in C-reactive protein (CRP) levels." (PMID 32612961, 2020). "Inflammatory markers and cytokines, including C-reactive protein (CRP), ferritin, and interleukin (IL)-6, have been significantly elevated in multiple cohorts of patients infected with COVID-19." (PMID 32664919, 2020). "In our study, corticosteroid-treated patients had more advanced COVID-19 compared with corticosteroid-untreated patients, as reflected by poorer blood laboratory parameters (lymphocytes, CRP, and LDH) and more extensive chest CT involvement." (PMID 32719766, 2020). "C-reactive protein was also identified as an important feature for predicting a severe course of disease in hospitalized COVID-19 patients." (PMID 32895375, 2020). "Blood levels of the prototypic acute phase reactant, C-reactive protein (CRP), which is hepatically synthesized and released in response to interleukin-6 stimulation, is markedly elevated in patients with COVID-19." (PMID 32588812, 2020). "The potential risk factors of males, older age, with comorbidities, low T lymphocyte level and high level of NLR, CRP, IL-6 can help to predict clinical progression of COVID-19 at an early stage." (PMID 32620125, 2020). "The findings suggest that CRP elevation and a previous history of comorbidities are important clinical characteristics and independent predictors of severe COVID-19." (PMID 32802219, 2020). "The risk factors for severe cases of COVID-19 in Guangzhou included older age, Wuhan exposure history greater than 2 weeks, diarrhea, elevated Myoglobin, elevated WBC and CRP, and CKD." (PMID 32805730, 2020).
COVID-19 (continued). "Among all univariable parameters, lymphocytes, CRP, and LDH were significantly independent risk factors of COVID-19 severity." (PMID 32633729, 2020). "Elevation of C-reactive protein (CRP) was a more common phenomenon in patients with COVID-19 than that in patients with influenza A H1N1 virus pneumonia." (PMID 32574297, 2020). "Our mild and moderate COVID-19 patients had elevated inflammatory markers (e.g., CRP, D-dimer, and ferritin), similar to cytokine release syndrome, with persistent fevers." (PMID 33239068, 2020). "In the mild COVID-19 group, some patients had normal content of C4, CRP and PA, but lower content of C3 and higher content of SAA." (PMID 32713370, 2020). "The severity of chest CT lesions was positively correlated with hs-CRP and D-dimer levels which significantly increased in the patients with severe COVID-19." (PMID 32968416, 2020). "Some COVID-19 patients typically show increased IL-6 and C-reactive protein levels before death, indicative of the progress of inflammation in the COVID-19 heart." (PMID 33232272, 2020). "The evidence suggests that C-reactive protein (CRP) levels are increased significantly by COVID-19 due to the inflammatory reaction." (PMID 33244370, 2020). "Other than that, lymphopenia, high D-dimer level, high C-reactive protein level and characteristic CT findings, as well as RNA detection assays can help differentially diagnose COVID-19 from a common infection." (PMID 32468202, 2020). "The expert consensus statement for children with COVID-19 has indicated that most patients display increased CRP and LDH levels but normal procalcitonin levels." (PMID 32865382, 2020). "In a study of 426 COVID-19 patients, C-Reactive Protein (CRP) was noted to be increased in 75–93% of patients, more commonly in patients with severe disease." (PMID 33520910, 2020). "Analysis of inflammatory parameters in COVID-19 patients showed that, compared with mild cases, severe cases gained higher C-reactive protein (CRP) (P = 0.0078), procalcitonin (PCT) (P < 0.001), and lower complement C1q (P < 0.001)." (PMID 32669467, 2020). "Blood tests in pregnant women revealed regular COVID-19 markers, such as lymphopenia, neutrophilia, and elevated C-reactive protein level in pregnant women." (PMID 32733490, 2020). "Observations from another 150 patients in Wuhan revealed that those who died of COVID-19 complications had higher serum levels of C-reactive protein (CRP), interleukin (IL)-6 and ferritin, suggesting an underlying hyperinflammatory process." (PMID 32754159, 2020). "Inflammatory markers, such as leukocytes, C-reactive protein, and procalcitonin are significantly enhanced among COVID-19 patients who are in cardiac injury." (PMID 33178016, 2020). "Increased C-reactive protein (CRP) and high-sensitivity CRP is reported in the majority of COVID-19 patients." (PMID 32695683, 2020). "We considered high C-reactive protein (CRP) in severe COVID-19 patients (CRP ≥ 1 mg/dL) as a surrogate of a cytokine storm." (PMID 32876941, 2020). "A recent study with severe COVID-19 patients found a direct link between C-reactive protein (CRP) and inflammation where higher CRP levels in the blood show greater inflammation." (PMID 32973505, 2020). "Clinicians should consider older men patients with comorbidities, lymphopenia, and a high CRP rate to predict severe COVID-19 at an early stage of hospitalization." (PMID 33033687, 2020). "A COVID-19 severity score ranging from 0 to 10, consisting of age, oxygen saturation, mean arterial pressure, blood urea nitrogen, C-Reactive protein, and the international normalized ratio was developed." (PMID 33028914, 2020). "Recently, some studies have shown that cancer patients with COVID-19 have higher level of CRP, and higher neutrophil counts, D-dimer and LDH are associated with poor prognosis." (PMID 33192519, 2020).
COVID-19 (continued). "The risks for death were related to later onset of treatment for COVID-19, severe/critical COVID-19, age, elevated basal CRP and elevated lactate dehydrogenase." (PMID 33432270, 2020). "In addition, the use of a panel of laboratory tests for inflammation,hypercoagulability, and organ damage (e.g., CRP, ferritin, D-dimer, cardiac enzymes,liver enzymes, and creatinine) might assist in the early identification andmanagement of this COVID-19–associated condition." (PMID 33031361, 2020). "The aim of this study was to observe the association of coagulopathy (D-dimer) with cytokines [i.e., neutrophil-to-lymphocyte ratio (NLR), IL-6, and C-reactive protein (CRP)] and CT imaging in COVID-19-infected patients." (PMID 33195321, 2020). "Studies of COVID-19 patients' serum show lymphopenia and a marked increase in inflammatory markers such as interleukin-6 (IL-6) and C-reactive protein (CRP)." (PMID 33195363, 2020). "Recently, a study of 274 cases of patients with COVID-19 found that patients who were deceased generally had markedly higher level of CRP and LDH than recovered patients." (PMID 32750000, 2020). "As part of clinical care, D-dimer, procalcitonin, ferritin, lactate dehydrogenase, and C-reactive protein levels were measured in moderate and severe COVID-19+ individuals." (PMID 32669287, 2020). "We noticed that COVID-19 patients had raised inflammatory markers in terms of raised CRP and ferritin." (PMID 33043251, 2020). "In general, the laboratory findings in the COVID-19 elderly population revealed lymphopenia, elevated inflammatory markers (CRP and ESR), as well as elevated LDH and D-dimers." (PMID 32765959, 2020). "Although we demonstrated the adverse roles of pro-inflammatory neutrophils and CRP in cancer patients with COVID-19, our research still had several limitations." (PMID 33192519, 2020). "A last possible phenotype would be a COVID-19 specific phenotype, associated with lymphopenia and high levels of PCT and CRP, and characterized by bilateral (diffuse) frontally localized, pressing, and intense pain, and hypersensitivity to stimuli." (PMID 33391152, 2020). "Laboratory findings most consistent with COVID-19 were lymphocytopenia, elevated C reactive protein and elevated erythrocyte sedimentation rate." (PMID 32563999, 2020). "Our study revealed that severe COVID-19 patients with comorbidities had higher levels of inflammatory indices, including blood interferon-γ, interleukin (IL)-6 and c-reactive protein levels as well as the erythrocyte sedimentation rate." (PMID 33232277, 2020). "Unexpectedly, a cut-off of 91.39 mg/L for serum CRP levels had a sensitivity of 81.3% and a specificity of 88.2% for predicting death in patients with COVID-19." (PMID 32805722, 2020). "IL-6 also induces hepatocytes to synthesize acute phase reactive protein, especially Serum amyloid A (SAA) and C-reactive protein (CRP), which were significantly elevated in COVID-19 patients." (PMID 33195318, 2020). "In our study, we presented the clinical characteristics of 155 patients with COVID-19 and reported that patients had increased CRP, IL-6, hsTnI, D-dimer, and β2-MG with increased severity of the disease." (PMID 32574334, 2020). "For patients with COVID-19, the number of white blood cells, neutrophils, as well as levels of procalcitonin, C-reactive protein, and other inflammatory indices, are significantly higher in the intensive care unit (ICU) cases than in non-ICU cases." (PMID 32754163, 2020). "Meanwhile, studies have reported that patients infected with COVID-19 show increased levels of pro-inflammatory neutrophils, procalcitonin, CRP and IL-6." (PMID 33192519, 2020). "Many studies reported a correlation between high levels of hs-CRP and mortality rate in COVID-19 patients." (PMID 33392056, 2020). "Our analysis showed that CRP is significantly elevated as compared to the mild course of the disease in severe cases of COVID-19 and was an important predictor of severity of the disease." (PMID 32913691, 2020).
COVID-19 (continued). "Pre-infectious signs of inflammation, such as elevated values for CRP (C-reactive protein), represent a common aggravating factor in COVID-19." (PMID 32784601, 2020). "The inflammatory pathways are activated during COVID-19, and therefore parameters like C-reactive protein (CRP), ferritin, procalcitonin, fibrinogen, interleukin-6 (IL-6) were studied as prognostic factors." (PMID 32748880, 2020). "To further examine if higher inflammation contributes to disease severity, we next analyzed cytokine profiles and CRP expression of COVID-19 patients sub-grouped based on disease severity." (PMID 32475230, 2020). "Early positive investigation results included a positive COVID-19 swab test, raised CRP, ferritin, D-dimer and TNF-alpha, characteristic of proinflammatory states." (PMID 32696735, 2020). "Other studies have shown certain biomarkers such as ferritin, lactate dehydrogenase (LDH), D-dimer, and C-reactive protein (CRP) to predict COVID-19 severity." (PMID 32997700, 2020). "In a retrospective single-center study involving 94 confirmed COVID-19 patients, therapeutic regimens of IFN-α + LPV/r and IFN-α + LPV/r + RBV were found to be beneficial for reducing IL-6 and C-reactive protein levels in COVID-19 patients." (PMID 34765999, 2020). "The patients with severe COVID-19 develop an overwhelming state of inflammation (elevated marker: C-reactive protein) with multiorgan dysfunction that has been labeled COVID-19 cytokine storm syndrome (CSS)." (PMID 32848802, 2020). "In this review, stroke patients with COVID-19 consistently presented with an elevated level of D dimers, CRP, ferritin, LDH, troponin, ESR, fibrinogen, and with positive antiphospholipid antibodies reported in some studies." (PMID 33123082, 2020). "The distribution of peak temperature (>38°C) on set, myalgia or arthralgia and C-reactive protein (≥10 mg per L) were the prognostic factors to identify the progression of COVID-19 patients with mild or moderate type." (PMID 33052140, 2020). "LDH, CRP and age can be used for identification of severe patients with COVID-19 on hospital admission." (PMID 32746957, 2020). "CRP is widely considered as a surrogate of IL-6 bioactivity and the role of IL-6 in inducing pro-inflammatory cytokines and the development of cytokine storm in COVID-19 patients indicates the importance of CRP in the assessment of the related complications." (PMID 32876941, 2020). "Higher NLR, C-Reactive protein, serum ferritin, D-dimer and fibrinogen levels are associated with poor prognosis of AIS in COVID-19 with 75% of patients dying or being severely disabled at present." (PMID 33101164, 2020). "The severe COVID-19 patients had statistically higher body temperature and CRP levels and a wider range of pulmonary involvement after symptoms appeared than the moderate ones." (PMID 33204376, 2020). "Multivariate analysis showed that neutrophil counts (OR, 1.286; 95% CI, 1.007–1.536; p = 0.005) and CRP (OR, 1.047; 95% CI, 1.016–1.079; p = 0.003) levels were found to be independent predictors of adverse clinical outcomes of COVID-19." (PMID 33192519, 2020). "This cohort study found an increased incidence of LA positivity in patients with COVID-19 after adjusting for CRP levels." (PMID 32785632, 2020). "From cardiovascular disease to cancer to acute kidney injury high CRP levels have been shown to correlate with worse prognosis, and recent evidence indicates CRP is a very good predictor of adverse outcomes for COVID-19 patients." (PMID 33633738, 2020). "In conclusion, on-admission platelet count, ALT and AST activities, CRP concentration, and the presence of acute and CLDs predicted the severe course of COVID-19." (PMID 33282888, 2020). "The values for cytokines and CRP were significantly higher in patients with COVID-19 than those in healthy controls." (PMID 32793246, 2020).